ROBO1 (roundabout guidance receptor 1)
Diseases named in the same sentence as ROBO1 in open-access papers (continued):
Sharing a sentence is not in itself a finding about the gene and the disease.
type 2 diabetes (3 papers, 2015 to 2025). "According to the literature study, some genes that are associated with developmental dyslexia, such as ROBO1, DCDC2, DYX1C1, and KIA0319, and some genes that are associated with type 2 diabetes CTNNB1, TCF7L2, and KIF3A had shown some connections with each other." (PMID 34674647, 2021).
acute myeloid leukemia (2 papers, 2019 to 2022). Acute myeloid leukemia (AML) is a group of neoplasms arising from precursor cells committed to the myeloid cell-line differentiation. "Acute myeloid leukemia patients were generally high expressers of ROBO1 and ROBO2 compared to the controls (p < 0.0001, p < 0.001, respectively)." (PMID 30820596, 2019).
age-related macular degeneration (2 papers, 2011 to 2024). Age-related loss of vision in the central portion of the retina (macula), secondary to retinal degeneration. "ROBO1 is a strong candidate gene for age-related macular degeneration (AMD) based upon its location under a linkage peak on chromosome 3p12, its expression pattern, and its purported function in a pathway that includes RORA, a gene previously associated with risk for neovascular AMD." (PMID 21998696, 2011).
alcohol dependence (2 papers, 2018 to 2021). Physical and psychological dependence on alcohol. "ROBO1 is one gene enriched in the axon guidance pathway, significantly associated with alcoholism and alcohol addiction." (PMID 33540941, 2021).
autism spectrum disorder (2 papers, 2022 to 2025). A spectrum of developmental disorders that includes autism, and Asperger syndrome. "The subnetwork included AS events of ROBO1 and CLIP1, both of which had neural-regulated micro-exons (exons 3–27 nt) involved in an AS interaction network associated with an autism spectrum disorder in a previous study." (PMID 35085775, 2022).
B cell lymphoma (2 papers, 2021). "Most engineered CAR-NK cells are directed against blood-related malignancies, such as CD19 for B cell lymphomas, CD22 for refractory B-cell lymphomas and solid tumors, NKG2D-ligand for pancreatic cancers, and CD33 and ROBO1 specific BiCAR-NK/T for malignant and metastatic solid tumors." (PMID 34925314, 2021).
cholangiocarcinoma (2 papers, 2022 to 2023). A carcinoma that arises from the intrahepatic biliary tree (intrahepatic cholangiocarcinoma) or from the junction, or adjacent to the junction, of the right and left hepatic ducts (hilar cholangiocarcinoma). "Recently, inactivating mutations in SLIT2 and ROBO1 were identified in a subset of relapsing cholangiocarcinoma patients." (PMID 37311584, 2023).
chordoma (2 papers, 2020 to 2021). Chordomas are rare malignant tumors arising from embryonic remnants of the notochord in axial skeleton. "The molecular mechanisms underlying the relationship among NONHSAT024778, miR-1290 and Robo1 were determined to help in developing potential biomarker and therapeutic targets in the prognosis and treatment of patients with chordoma." (PMID 33767589, 2021). "In summary, NONHSAT024778 functions as an oncogene promoting the proliferation, migration, and invasion of chordoma cells, and contributes to chordoma progression by up-regulating Robo1 via sponging miR-1290 in vitro." (PMID 33767589, 2021). "Bioinformatics analysis showed that NONHSAT024778 acted as ceRNA to regulate Robo1 via sponging miR-1290 in chordoma cells, thereby promoting chordoma cell malignant progression." (PMID 33767589, 2021). "The specific regulatory role of the NONHSAT024778/miR-1290/Robo1 axis in chordoma must be extensively explored in further studies." (PMID 33767589, 2021). "Bioinformatics analysis revealed that novel lncRNA-NONHSAT024778 acted as a ceRNA to regulated roundabout guidance receptor 1 (Robo1) via sponging miR-1290 in chordoma." (PMID 33767589, 2021). "To date, the expression and function of Robo1 in human chordoma remain unexplored." (PMID 33767589, 2021). "Furthermore, rescue experiments determined that the effect of NONHSAT024778 knockdown on the proliferation, migration, and invasion of chordoma cells can be partly reversed by miR-1290 inhibition or Robo1 re-expression in U-CH1 cells." (PMID 33767589, 2021). "The oncogenic role of Robo1 in chordoma was investigated as follows." (PMID 33767589, 2021). "Therefore, NONHSAT024778 governs chordoma growth by sponging miR-1290 to regulate Robo1 in vivo." (PMID 33767589, 2021). "U-CH1 cells were stably co-transfected with si-NONHSAT024778/Lv-Robo1 or Lv-NONHSAT024778/si-Robo1 and control vector and then were subcutaneously injected into NOD/SCID mice separately to further confirm the effects of NONHSAT024778/miR-1290/Robo1 on chordoma cell growth in vivo." (PMID 33767589, 2021).
colitis (2 papers, 2020 to 2024). Inflammation of the colon. "Based on the GEO analysis, we next investigated whether Slit2/Robo1 signaling affects DSS-induced colitis in Slit2-Tg and Robo1/2 +/- mice." (PMID 32398956, 2020). "Robo1, the receptor for the secreted glycoprotein Slit2, mediates DSS-induced colitis by activating the autophagy of Lgr5+ ISCs." (PMID 38891118, 2024).
diabetic nephropathy (2 papers, 2010 to 2022). "Slit-2/Robo1 signaling is involved in early diabetic nephropathy and may be an effective therapeutic target for abnormal angiogenesis in early diabetic nephropathy." (PMID 35813663, 2022).
endometriosis (2 papers, 2021 to 2025). The growth of functional endometrial tissue in anatomic sites outside the uterine body. "Moreover, a significant downregulation of several potential targets, including CDK6, BCCIP, PTEN, TCF7L1, TCF7L2, ROBO1, COL4A2, E‐Cadherin, and N‐Cadherin, was observed in the transfected cells and endometriosis patients." (PMID 40135061, 2025).
HIV-1 infection (2 papers, 2009 to 2013). The type species of lentivirus and the etiologic agent of acquired immunodeficiency syndrome (AIDS). "We, therefore, assessed the role of Robo1 in Slit2N-mediated inhibition of HIV-1 infection." (PMID 23294842, 2013). "To verify that the siRNA targeting Robo1 in naïve T cells significantly reduced viral production during HIV-1 infection, we next examined whether Robo1 expression was successfully knocked down upon siRNA treatment using western blot." (PMID 19788744, 2009).
lymphoma (2 papers, 2005 to 2011). A malignant (clonal) proliferation of B- lymphocytes or T- lymphocytes which involves the lymph nodes, bone marrow and/or extranodal sites. "Several evidences, including the detection of ROBO1 methylation in primary solid tumours and the predisposition of mice carrying an inactivated ROBO1 allele to generate lymphomas, support the role of this gene as a classical TSG." (PMID 21603610, 2011).
metastatic tumors (2 papers, 2021 to 2023). "PDE4DIP, ROBO1, and NOTCH4 mutations were observed only in metastatic tumors, whereas mutations specific to primary tumors were undetectable." (PMID 34158601, 2021).
myelodysplastic syndrome (2 papers, 2015 to 2019). A clonal hematopoietic disorder characterized by dysplasia and ineffective hematopoiesis in one or more of the hematopoietic cell lines. "Additionally, using whole-exome and targeted sequencing in 209 patients with myelodysplastic syndrome (MDS) found ROBO1 and ROBO2 mutations in 26 (12.4%) patients." (PMID 30820596, 2019).
ovarian tumor (2 papers, 2024 to 2025). "ROBO1-NK cells demonstrate remarkable efficacy in lysing primary cells and organoids derived from patient-specific ovarian tumor tissues." (PMID 39069888, 2024).
periodontitis (2 papers, 2020 to 2024). An acute or chronic inflammatory process that affects the tissues that surround and support the teeth. "Our results suggest the possible role of SLIT2/ROBO1 signaling of the pathophysiology of periodontitis via activation of MAPK p38 signaling." (PMID 32760720, 2020). "A limitation of this study is that we did not analyze which isotope of SLIT2 regulates the pathophysiology of periodontitis and whether ROBO1 is the key receptor for SLIT2-mediated effect on periodontitis." (PMID 32760720, 2020). "However, our ongoing study on Robo1 knockout periodontitis mice will address these limitations." (PMID 32760720, 2020). "In this study, we found that both SLIT2 and ROBO1 were upregulated in periodontitis, suggesting the possible role of SLIT2/ROBO1 axis on escalation of inflammation and disease progression in periodontitis." (PMID 32760720, 2020). "SLIT2 overexpression upregulated Robo1 and MAPK signaling related factors’ expression in PAPT during periodontitis." (PMID 32760720, 2020). "In periodontitis, the overexpression of Slit2 may exacerbate inflammation and immune cell infiltration, potentially activating p38/MAPK through the Slit2/Robo1 signaling pathway." (PMID 39768930, 2024).
preeclampsia (2 papers, 2019 to 2025). Preeclampsia is a hypertensive disorder of pregnancy that is characterized by new-onset hypertension with proteinuria presenting after 20 weeks of gestation, and depending on mild or severe forms may initially present with severe headache, visual disturbances, and hyperreflexia. "Although late-onset preeclampsia is not as strongly associated with placental vascular dysfunction as early-onset preeclampsia, genes such as CP, IGFBP7, CDH13, ROBO1, UNC5C, NRXN3, and ITGA1 suggest subtle changes in angiogenic pathways." (PMID 41444673, 2025).
proliferative diabetic retinopathy (2 papers, 2011 to 2017). Advanced retinopathy due to diabetes mellitus characterized by the formation of new vessels in the retina. "The expression of Slit2 mRNA, Robo1 mRNA, and VEGF mRNA was significantly higher in human fibrovascular proliferative diabetic retinopathy membranes than in the control membranes." (PMID 28973045, 2017). "Because rodents do not develop proliferative diabetic retinopathy, we selected the patients with proliferative diabetic retinopathy (PDR) to examine the roe of Slit2 and Robo1 in proliferative stage." (PMID 28973045, 2017). "Additionally, FVMs and vitreous fluid from patients both with proliferative diabetic retinopathy (PDR) and without (control) were used to investigate the expression of Slit2 and Robo1 in the proliferative stage of DR." (PMID 28973045, 2017).
rheumatoid arthritis (2 papers, 2020 to 2023). A chronic, systemic autoimmune disorder characterized by inflammation in the synovial membranes and articular surfaces. "In addition, hsa-miR-218-5p induces osteogenic differentiation of rheumatoid arthritis synovial fibroblasts by regulating ROBO1/DKK-1 pathway." (PMID 37525657, 2023). "However, we also argue against a suggested pro-osteogenic role of miR-218 due to targeting of ROBO1 reported for rheumatoid arthritis FLS." (PMID 33303006, 2020).
Tetralogy of Fallot (2 papers, 2018 to 2021). A congenital cardiac malformation comprising pulmonary stenosis, overriding aorta, ventricular septum defect, and right ventricular hypertrophy. "Recently, using whole exome sequencing, loss of function variants in ROBO1 have been linked to ventricular septal defects and tetralogy of Fallot." (PMID 29538649, 2018). "Recently, loss of function variants in ROBO1 have also been linked to ventricular septal defects and tetralogy of Fallot in patients." (PMID 29538649, 2018).
aortic regurgitation (1 paper, 2023). "In regards to BAV adult patients with variants in ROBO1, ROBO2, SLIT1 and SLIT3 genes, the presence of BAV-related complications such as aortic regurgitation, aortic stenosis, and AscAA was checked." (PMID 36855159, 2023).
brain cancer (1 paper, 2010). A primary or metastatic malignant neoplasm affecting the brain. "Studies have implicated Robo1 in liver, breast, and brain cancers." (PMID 21301049, 2010).
cervical tumors (1 paper, 2012). "The alteration frequencies of ROBO1 and ROBO2 increased significantly from CIN to stage I/II tumors, indicating that these receptors were inactivated during the development of early invasive cervical tumors." (PMID 22719878, 2012). "Microsatellite size alterations (MA) of ROBO1 and SLIT2 were infrequent in cervical tumors, unlike HNSCC." (PMID 22719878, 2012).
childhood apraxia of speech (1 paper, 2016). "These include balanced translocations disrupting ROBO1 and DYX1C1 in dyslexic cases and translocations and deletions affecting FOXP2 in a severe form of speech and language disorder, involving childhood apraxia of speech (CAS)." (PMID 27186239, 2016).
childhood cancers (1 paper, 2025). "ROBO1 and GPC3 are also expressed on the cell membrane in some types of cancer, and the five antigens also cover various pediatric cancers." (PMID 40076777, 2025). "Our CAR-T therapy targeting five common membrane protein cancer antigens—EphB4, CLDN1, LAT1, ROBO1, and GPC3—may be effective against many solid tumors, including childhood cancers." (PMID 40076777, 2025).
colorectal tumors (1 paper, 2020). "ROBO1 was selected because it is reportedly lost in some colorectal tumors and because of its proposed role as an inhibitor of cell migration and epithelial-to-mesenchymal transition (EMT)." (PMID 32778592, 2020).
congenital diaphragmatic hernia (1 paper, 2024). A posterolateral defect of the diaphragm that allows passage of abdominal viscera into the thorax, leading to respiratory insufficiency and persistent pulmonary hypertension with high mortality. "In a mouse model of congenital diaphragmatic hernia with genetic ablation of Robo1 and Robo2, PNEC product secretion was increased, which led to increased infiltration of macrophages and other immune cells into the lung." (PMID 38813849, 2024).
congenital heart disease (1 paper, 2023). "Loss-of-function ROBO1 variants have been linked to Tetralogy of Fallot, a congenital heart disease." (PMID 36942388, 2023). "Knockouts for Sema3, Nrp1, or PlxnD1 and Robo1 mutant mice show ventricular septal defects (VSDs) and outflow tract defects, suggesting dysfunction of these guidance pathways may contribute to congenital heart disease (CHD)." (PMID 36942388, 2023).
congenital hydronephrosis (1 paper, 2022). Congenital hydronephrosis is a renal urinary disease characterized by distension and dilation of the renal pelvis and calyces secondary to various congenital obstructive malformations of the kidneys and urinary tract that can evolve to renal atrophy. "A de novo pathogenic variant c.2883-1G>T in ROBO1 was detected in a patient from Sri Lanka (cardio-12.A) with multiple cardiac defects and an extracardiac phenotype of congenital hydronephrosis." (PMID 36011280, 2022).
cutaneous melanoma (1 paper, 2016). A primary melanoma arising from atypical melanocytes in the skin. "Down-regulation of ROBO1 is part of a molecular signature that predicts the metastatic risk associated with cutaneous melanoma, therefore we examined the survival of patients with SLIT3 mutations." (PMID 27095580, 2016).
ductal carcinoma (1 paper, 2015). "Our results demonstrated that Invasive ductal carcinoma patients with low expression of Slit2 or Robo1 exhibited worse prognosis and brain-specific metastasis, but not liver, bone or lung." (PMID 26400100, 2015).
Ewing sarcoma (1 paper, 2022). A small round cell tumor that lacks morphologic, immunohistochemical, and electron microscopic evidence of neuroectodermal differentiation. "Silencing of Slit2 receptors, Robo1 and Robo2, inhibited Ewing sarcoma growth as well." (PMID 36533189, 2022).
glaucoma (1 paper, 2024). Increased pressure in the eyeball due to obstruction of the outflow of aqueous humor. "However, there are currently no publications reporting the association between ROBO1 and the onset of glaucoma." (PMID 39221148, 2024).
head-neck cancer (1 paper, 2017). "Co-expression analysis revealed that CAP1 was coexpressed with TUBA1B both in pancreatic and head-neck cancer, as well as with CFL1, CFL2, DSTN, and ROBO1, according to STRING analysis." (PMID 28423713, 2017). "The co-expression analysis revealed that CAP1 was coexpressed with TUBA1B in pancreatic and head-neck cancer, as well as with CFL1, CFL2, DSTN, ACTB, ACTG1, and ROBO1, according to the STRING analysis." (PMID 28423713, 2017).
Hyperglycemia (1 paper, 2017). An increased concentration of glucose in the blood. "Decreased expression of axon guidance pathway genes, Robo1, Ntn1, Ntng1, Nrp1, and Efnb3 in NSCs exposed to hyperglycemia was suggestive that miRNAs could target and deregulate the axonal guidance pathway as predicted by the pathway analysis." (PMID 28798665, 2017).
Hypoglycemia (1 paper, 2023). A decreased concentration of glucose in the blood. "Placenta glucose transfer, DNA methylation from umbilical cord blood and neonatal blood, the same source of different cells, and Slit-2/Robo1 signaling all might be involved in the pathogenesis of UACBG predicting neonatal hypoglycemia." (PMID 38129821, 2023).
kidney cancer (1 paper, 2018). Primary or metastatic malignant neoplasm involving the kidney. "In case of the Robo1 gene too, hypermethylation was found in breast and kidney cancer cells." (PMID 29864155, 2018).
liver diseases (1 paper, 2024). "Our observation also suggests that restoring NMD activity may show a protective effect in liver diseases by suppressing the expression of disease-related genes, such as Robo1 and Ephb2." (PMID 39456836, 2024).
lymph node metastasis (1 paper, 2015). "Univariate analysis indicated that Slit2 expression, Robo1 expression, pathological grade, lymph node metastasis and cTNM were significantly associated with shortened OS." (PMID 26400100, 2015). "In multivariate Cox regression analysis, Slit2 and Robo1 were both independent prognostic factors for OS, when stratified by tumor size, pathological stage, lymph node metastasis, and cTNM." (PMID 26400100, 2015).
malignant glioma (1 paper, 2013). A grade III or grade IV glioma arising from the central nervous system. "Our findings indicate that this regulator of epithelial-mesenchymal transition orchestrates key features of cancer stem cells in malignant glioma and identify ROBO1, OLIG2, CD133 and MGMT as novel targets of the ZEB1 pathway." (PMID 23818228, 2013). "The axon guidance molecule ROBO1 can sever the anchorage of N-cadherin to the cytoskeleton, thereby increasing cellular motility, and is expressed in malignant glioma." (PMID 23818228, 2013).
mesothelioma (1 paper, 2010). A usually malignant and aggressive neoplasm of the mesothelium which is often associated with exposure to asbestos. "NCI-H28 mesothelioma cells exhibited robust Abl activity and Robo1 protein expression which were reduced by over 80% and 40%, respectively, by treatment with GNF-2." (PMID 21301049, 2010).
myeloid malignancies (1 paper, 2017). "Most of the significantly mutated genes were previously well documented either in MDS or other myeloid malignancies, although some were newly identified or re-confirmed as recurrently mutated genes in our analysis, such as ROBO1/2, IHIT3, KIF20B, PTPRD, ANKRD11 and DHX9." (PMID 28220884, 2017).
non-small cell lung carcinoma (1 paper, 2022). A group of at least three distinct histological types of lung cancer, including non-small cell squamous cell carcinoma, adenocarcinoma, and large cell carcinoma. "Notably, very recent works have pointed to the important role of ROBO1 expression in driving oncogenic properties and cisplatin resistance in bladder and non-small cell lung cancer, respectively." (PMID 36057630, 2022).
Osteochondroma (1 paper, 2018). A common, benign cartiliginous neoplasm arising from the metaphysis of bone. "Next, we detected the expression patterns of ROBO1 and SLIT2 in OS (n = 40) and osteochondroma (OC) (n = 10) tissue specimens by IHC staining." (PMID 29523788, 2018).
Osteopenia (1 paper, 2023). Osteopenia is a term to define bone density that is not normal but also not as low as osteoporosis. "Mice that knockdown Slit3 or its receptor Robo1 exhibit an osteopenia phenotype as a result of increased bone resorption and reduced bone formation." (PMID 36636821, 2023).